CSMD1 (CUB and Sushi multiple domains 1)
Diseases named in the same sentence as CSMD1 in open-access papers (continued):
Sharing a sentence is not in itself a finding about the gene and the disease.
oral squamous cell carcinoma (2 papers, 2018 to 2019). "Deletions in CSMD1, a putative tumor suppressor implicated in diverse cancers, were found in a substantial fraction (26%) of oral squamous cell carcinoma patients." (PMID 30545040, 2018).
polymicrogyria (2 papers, 2022 to 2024). A developmental brain abnormality characterized by an excessive amount of small convolutions on the surface of the brain and cognitive dysfunction. "In this published case, biallelic CSMD1 (p.S188N; p.Q1782K) variants present with polymicrogyria, similar to polymicrogyria and thin corpus callosum observed in P1 (p.E138K; p.R213L)." (PMID 38816421, 2024). "Moreover, we have postulated a potential association between rare CSMD1 variants and cerebellar agenesis and/or polymicrogyria that needs to be further investigated." (PMID 35162247, 2022). "We have identified some associations already documented, such as the relation between cerebellar agenesis and the cognitive and psychiatric profile, the relation between polymicrogyria and some cognitive characteristics and the relation between CSMD1 variants and cognitive and psychiatric symptoms." (PMID 35162247, 2022).
psychosis (2 papers, 2022 to 2025). "Further, reduced CSMD1 mRNA expression has been observed in peripheral blood of SZ patients and common genetic variation within CSMD1 has been associated with psychosis proneness in the general population, as well as memory functioning in SZ and healthy individuals." (PMID 35532796, 2022). "Furthermore, supported by recent documentation, the dysregulation of CSMD1 complement components may contribute to psychosis and is associated with cognitive function." (PMID 40362533, 2025). "The biological relationship between C4A and CSMD1 components and their role in shared biochemical processes of the complement system is strengthened by studies examining psychosis-related behavioral and cognitive phenotypes in mice." (PMID 35532796, 2022).
triple-negative breast carcinoma (2 papers, 2021 to 2024). An invasive breast carcinoma which is negative for expression of estrogen receptor (ER), progesterone receptor (PR), and human epidermal growth factor receptor 2 (HER2). "The current study aimed to elucidate the molecular mechanism underlying the effect of CSMD1 in highly invasive triple negative breast cancer (TNBC)." (PMID 34404439, 2021). "In addition, higher mRNA levels of CSMD1 tend to be associated with better outcome of triple negative breast cancer patients treated with chemotherapy." (PMID 34404439, 2021). "We previously reported on the interaction between CSMD1 and EGFR in triple-negative breast cancer and found that CSMD1 overexpression led to increased cell apoptosis following treatment with gefitinib, an EGFR inhibitor." (PMID 38561856, 2024). "Forced expression of CSMD1 in human BT-20 and MDA-MB-231 triple negative breast cancer (TNBC) cells significantly inhibited their migration, adhesion and invasion, while stable silencing of CSMD1 expression in hormone-dependent T47D cells enhanced their migratory, adherent and clonogenic abilities." (PMID 34404439, 2021).
adenoma (1 paper, 2013). A neoplasm arising from the epithelium. "In order to properly determine the timelines for CSMD1 and KRAS mutations, carful sequence analysis of early lesions such as adenomas will be required." (PMID 23505554, 2013).
agoraphobia (1 paper, 2013). An anxiety disorder characterized by an intense, irrational fear of venturing out into open places or situations in which help (or escape) might not be available should excessive anxiety or panic symptoms develop. "However, we cannot rule out that increased object contacts (exploration) are due to the observed agoraphobia-like behavior of Csmd1 KO mice, which leads to avoidance of open space and, therefore, might mask possible defects in object preference in the KO mice." (PMID 24244513, 2013).
benign adult familial myoclonic epilepsy (1 paper, 2019). "CSMD1 has been associated to diseases such as Benign Adult Familial Myoclonic Epilepsy (Malacards, MCID: BNG079) and Smallpox (MCID: SML019)." (PMID 30677042, 2019).
brain tumor (1 paper, 2024). "Thus, reduced CSMD1 expression in gliomas could contribute to increased mutation patterns and accelerated brain tumor formation in mice." (PMID 38561856, 2024). "We also showed that the knockdown of Csmd1 in the RCAS/tv-a brain tumor model increased glioma formation in mice." (PMID 38561856, 2024). "The tumor suppressor function of CSMD1 was also validated using both the RCAS/tv-a brain tumor model in mice and data obtained from glioma patients." (PMID 38561856, 2024). "There was also reduced survival in PDGFB-induced brain tumors in mice when Csmd1 was downregulated." (PMID 38561856, 2024). "Additionally, we observed reduced CSMD1 levels in mouse brain tumor models and glioma patients and Csmd1 knockdown promoted brain tumor development in a PDGFB-induced glioma mouse model and orthotopic xenograft model." (PMID 38561856, 2024).
cerebellar agenesis (1 paper, 2022). "To our knowledge, this is the first description of the co-occurrence of rare variants of CSMD1 gene and the rare neurodevelopmental condition of cerebellar agenesis, therefore, we were interested in deeply characterizing the developmental cognitive and behavioral outcome of this patient." (PMID 35162247, 2022).
esophageal cancer (1 paper, 2023). A primary or metastatic malignant neoplasm involving the esophagus. "One published article revealed that the mutation of CSMD1 may promote the progression of esophageal cancer." (PMID 36761763, 2023).
gastric tumor (1 paper, 2022). "Cub and Sushi Multiple Domains-1 (CSMD1) acts as a tumor suppressor, whose low expression promotes the invasion of HNSCC and gastric tumor and is also correlated with a poorer prognosis of HNSCC." (PMID 35449571, 2022).
glioma (1 paper, 2024). A benign or malignant brain and spinal cord tumor that arises from glial cells (astrocytes, oligodendrocytes, ependymal cells). "Analysis of the TCGA cohort revealed that low expression of CSMD1 in glioma is linked to a decline in both overall survival (OS) time disease-free survival (DFS) time, non-co-deleted 1p/19q genotype and wt-IDH phenotype." (PMID 38561856, 2024). "Both pSTAT3-Y705 and pP65-Ser536 showed enrichment in the nuclear and/or cytoplasmic fractions of Ctrl glioma cells treated with TNF, in contrast to the CSMD1-overexpressing glioma cells." (PMID 38561856, 2024). "CSMD1 expression was analyzed in four distinct molecular subtypes of glioma namely classical, mesenchymal, neural and proneural subtypes as defined in TCGA." (PMID 38561856, 2024). "Taken together, CSMD1 emerges as a novel tumor suppressor in glioma that directly impacts the aggressiveness of cancer cells and regulates inflammatory pathways." (PMID 38561856, 2024). "IPA software was utilized to determine the biological pathways moderated by CSMD1 expression in glioma." (PMID 38561856, 2024). "The gene expression level of both IL6 and CXCL8 was also downregulated in the CSMD1-high group compared to the CSMD1-low group in glioma cohorts." (PMID 38561856, 2024). "In this study, we first revealed that elevating CSMD1 expression in glioma cell lines significantly suppressed crucial malignant traits including cancer cell proliferation, migration, invasion, and the properties linked with the cancer stem cell phenotype." (PMID 38561856, 2024). "H4, U-118 and U-87 cell lines were used to investigate the tumor suppressor function of CSMD1 in gliomas." (PMID 38561856, 2024). "CSMD1-overexpressing clones of H4 and U-87 glioma cells were more responsive to temozolomide treatment than their corresponding Ctrl clones, although not in U-118 glioma cells." (PMID 38561856, 2024). "Upregulation of CSMD1 expression in gliomas was positively correlated with increased OS following temozolomide treatment independent of IDH mutation or 1p/19q co-deletion status." (PMID 38561856, 2024). "Since CSMD1 is highly expressed in brain tissue, this study aimed to determine its potential role in glioma." (PMID 38561856, 2024). "We observed that the overexpression of CSMD1 increased the sensitivity of the glioma cell lines, H4 and U-87, to temozolomide treatment." (PMID 38561856, 2024). "According to our analysis, mesenchymal subtype gliomas exhibited decreased CSMD1 expression patterns in all three glioma cohorts." (PMID 38561856, 2024). "Various inflammatory cytokines, including TNF, CSF2, IL1A, IL17A, IL6, and IFNG, were predictively inhibited in glioma samples exhibiting high CSMD1 expression." (PMID 38561856, 2024). "A Western blot analysis performed on subfractionated U-118 and U-87 glioma cells following TNF treatment demonstrated that pP65-Ser536 was upregulated in the cytoplasmic fraction of Ctrl clones compared to CSMD1-overexpressing clones." (PMID 38561856, 2024). "In addition, the expression of CSMD1 decreased the colony formation ability of glioma cells in soft agar." (PMID 38561856, 2024). "Furthermore, overexpression of CSMD1 in glioma cell lines suppressed the aggressive phenotype and TNF/P65/IL-6 and IL-8/STAT3 pathways." (PMID 38561856, 2024). "Our investigation, which includes clinical correlations, experimental models, and in vivo validations, provides a comprehensive understanding of the complex function of CSMD1 in glioma progression and illuminates its potential as a therapeutic target and prognostic marker." (PMID 38561856, 2024). "Lastly, we determined whether CSMD1 expression could affect glioma formation using an orthotopic in vivo model." (PMID 38561856, 2024). "CSMD1 is typically less expressed in this subtype compared to other glioma subtypes." (PMID 38561856, 2024). "Importantly, ectopic expression of CSMD1 in glioma cell lines led to decreased aggressiveness in vitro." (PMID 38561856, 2024).
glioma (continued). "In vitro, overexpression of CSMD1 in glioma cell lines restrained the aggressive phenotype." (PMID 38561856, 2024). "Notably, the pSTAT3-Y705/β-actin and pSTAT3-Y705/total STAT3 (except U-87) ratios exhibited higher values in Ctrl clones of glioma cell lines than in CSMD1-overexpressing clones." (PMID 38561856, 2024). "CSMD1-overexpressing glioma cells created smaller and fewer tumorspheres." (PMID 38561856, 2024). "Consequently, a treatment plan that combines temozolomide with EGFR and TNF inhibition may represent an effective therapeutic approach for gliomas expressing CSMD1." (PMID 38561856, 2024). "Therefore, we overexpressed CSMD1 in three glioma cell lines namely H4, U-118 and U-87." (PMID 38561856, 2024). "Our study has identified CSMD1 as a tumor suppressor in gliomas and elucidated its role in TNF-induced neuroinflammation, contributing to a deeper understanding of glioma pathogenesis." (PMID 38561856, 2024). "We found that overexpression of CSMD1 in glioma cells resulted in a decrease in phosphorylation of both P65 and STAT3 as well as a decrease in secretion of both IL-6 and IL-8 when compared to the corresponding Ctrl glioma cells." (PMID 38561856, 2024). "Therefore, we treated glioma cells with temozolomide and/or lomustine in combination with TNF and compared the response of Ctrl and CSMD1-overexpressing clones." (PMID 38561856, 2024). "Based on this, it seems that CSMD1 holds a direct tumor suppressor function in gliomas independent of its complement-inhibitory role, as long as the glioma cell lines do not secrete substantial amounts of different complement proteins." (PMID 38561856, 2024). "The tumor suppressor role of CSMD1 has been demonstrated in several cancers but its role in glioma has not been determined." (PMID 38561856, 2024). "Attenuated CSMD1 expression in HGG samples may modify the cytokine profile of glioma cells induced by TNF, thereby potentially aligning with the immunosuppressive phenotype in the glioma microenvironment." (PMID 38561856, 2024). "However, CSMD1 did not have a significant effect on U-118 cells, compared to the other glioma cell lines used in this study." (PMID 38561856, 2024).
Huntington disease (1 paper, 2024). Huntington disease (HD) is a rare neurodegenerative disorder of the central nervous system characterized by unwanted choreatic movements, behavioral and psychiatric disturbances and dementia. "KLHDC4 (cg08087060) is associated with Huntington’s disease, and CSMD1 (cg20912923) is related to learning and memory." (PMID 38663907, 2024).
keratoconus (1 paper, 2020). A degenerative, structural disorder of the eye, characterized by a cone-shaped protrusion of the cornea. "Specifically, we selected seven keratoconus-susceptibility genes (CDH13, SMAD3, ADAM12, CSMD1, NRXN1, CPLX2, and WWOX) for further analysis." (PMID 32737415, 2020).
lymph node metastasis (1 paper, 2020). "Similarly, deletion of CSMD1 gene has been associated with lymph node metastasis and poor prognosis in several cancers and is seen commonly in smokers." (PMID 32131500, 2020).
metastatic disease (1 paper, 2022). "In support of this, we found recurrent deletion of CSMD1 in the PDXs models and its associated with metastatic disease and survival." (PMID 36153537, 2022). "However, since we are comparing unmatched cohorts of primary and metastatic disease and relying on different platform to detect copy number, further studies on the match primary and metastatic disease based on the same platform is needed to confirm the roles of CSMD1 in metastatic breast cancer." (PMID 36153537, 2022).
oesophageal cancer (1 paper, 2022). "An oesophageal cancer study found CSMD1 mutated cancers were associated with a high tumour mutation burden (TMB)." (PMID 36553598, 2022). "This study also found CSMD1 wild-type oesophageal cancer patients were more susceptible to paclitaxel chemotherapy." (PMID 36553598, 2022).
Onset (1 paper, 2020). The age group in which disease manifestations appear. "The contribution of the complement system in PD is also evident from whole-exome sequencing analyses that identified mutations in the CUB and Sushi multiple domains 1 (CSMD1) gene in patients with familial late onset PD." (PMID 33291304, 2020).
oral cancer (1 paper, 2017). "The rationale of choosing these CNA associated genes was basically due to LRP12, TPM2, EGFR, CCND1 being matched with ICGC and TCGA databases whereas FSCN1, CLPTM1L, CHL1 and CSMD1 had been found to be associated with oral cancer." (PMID 28384287, 2017).
osteoarthritis (1 paper, 2021). A noninflammatory degenerative joint disease occurring chiefly in older persons, characterized by degeneration of the articular cartilage, hypertrophy of bone at the margins and changes in the synovial membrane. "The SNP rs1983474 of CSMD1 has been revealed to be connected with variation in urinary C-telopeptide of type II collagen (u CTX-II) levels in osteoarthritis which was a significant independent predictor of falls in patients with PD." (PMID 33628416, 2021). "The rs1983474 within CSMD1 has been revealed to be connected with variation in urinary C-telopeptide of type II collagen (u CTX-II) levels in patients with osteoarthritis." (PMID 33628416, 2021).
premature ovarian failure (1 paper, 2025). "CSMD1 expression has been previously associated with oocyte quality in mice and with premature ovarian failure in humans." (PMID 40834902, 2025).
serous ovarian cancer (1 paper, 2021). "Studies have shown that the locus containing CSMD1 is the most common in the homozygous deletion spectrum of high‐grade serous ovarian cancer, which may be a tumor suppressor gene for high‐grade serous ovarian cancer." (PMID 33934540, 2021).
Strabismus (1 paper, 2025). A misalignment of the eyes so that the visual axes deviate from bifoveal fixation. "The over-expression of CSMD1 in humans may disrupt retinogeniculate synaptic refinement and the area of binocular overlap, contributing to strabismus." (PMID 39858627, 2025).
tumor (83 papers, 2005 to 2026). "CSMD1 and CSMD2, which encode inhibitors of the complement system, have been proposed as tumor suppressor genes, with CSMD1 being the second most frequently mutated gene in BCC." (PMID 40725190, 2025). "The tumor suppressor role of CSMD1 has been implicated in various cancers including breast, head and neck, lung, gastric and colorectal cancers." (PMID 38561856, 2024). "Previously, we identified reduced CSMD1 expression in 79/275 (28.7%) of invasive ductal breast cancer patients, which were associated with high tumour grade and poor overall survival." (PMID 36553598, 2022). "Meanwhile, in vivo data verified that miR-642b-3p enhanced the tumor growth of GC cells, which was associated with blockade of CSMD1-dependent activation of the Smad signaling pathway." (PMID 35412956, 2022). "Research on the CUB and Sushi Multiple Domains 1 (CSMD1) gene, which is thought to be associated with tumour suppression and the immune system, has increased recently." (PMID 36553598, 2022). "It is conceivable that, under the selective pressure during cancer development, multiple CSMD1 variants reside in separate subclones within the same tumour population." (PMID 34168209, 2021). "CUB and Sushi multiple domains 1 (CSMD1) is a membrane-bound complement inhibitor, of which lncRNA, lncCSMD1, is associated with tumor progression of HCC cohorts." (PMID 34336665, 2021). "CSMD1 gene, encoding an inhibitor of the complement system, is believed to act as a tumour suppressor gene whose functions seems to be inactivated in many cancers." (PMID 34168209, 2021). "Lastly, CSMD1 is a membrane‐bound complement inhibitor, whose tumour‐suppressing properties have been linked to its short cytoplasmic tail that contains a tyrosine phosphorylation site." (PMID 33506581, 2021). "We assessed the association of the CSMD1 subgroup with tumor sites, human papillomavirus (HPV) status, gender, smoking status, regional lymph node (LN) metastasis and T stage." (PMID 30545040, 2018). "A similar observation was previously made using immunohistochemistry in which low CSMD1 protein levels were linked to high tumor grade and shorter overall survival." (PMID 27764775, 2016). "Human CUB and Sushi multiple domains 1 (CSMD1) is a membrane-bound complement inhibitor suggested to act as a putative tumor suppressor gene, since allelic loss of this region encompassing 8p23 including CSMD1 characterizes various malignancies." (PMID 27764775, 2016). "The varying subsets of mutation frequencies in CSMD1 allude to this belief that the multiple CSMD1 mutations arose from separate subclones in the same tumor population." (PMID 23505554, 2013). "Nevertheless, our observations indicate that CSMD1 nonsynonymous mutations provide tumor cells with a selective advantage, which operates independently of the advantage provided by KRAS mutations." (PMID 23505554, 2013). "Functional studies of CSMD1 will be required to further understand the mechanism by which CSMD1 mutations offer a selected advantage during tumor formation." (PMID 23505554, 2013). "It is important to note that tumor 517 had 10 somatic mutations to CSMD1, nine of which were nonsynonymous." (PMID 23505554, 2013).